MET (MET proto-oncogene, receptor tyrosine kinase)
Diseases named in the same sentence as MET in open-access papers (continued):
Sharing a sentence is not in itself a finding about the gene and the disease.
tumor (continued). "We selected KRAS, EGFR, BRAF, and MET mutations for inclusion in the multivariable model because they are among the most commonly altered driver mutations in LUAD and are known to significantly influence tumor behavior, prognosis, and response to targeted therapies." (PMID 40507306, 2025). "Additionally, MET JM domain mutations were found in lung but not in colon cancers, suggestive of a tumor site specificity." (PMID 40361420, 2025). "It is also essential to highlight that while higher levels of MET amplification tend to correlate with a better response to c-MET inhibitors, overall responses in MET amplified tumor are low, suggesting that wt c-MET may be a poor oncogenic driver even when overexpressed." (PMID 40361420, 2025). "Furthermore, an open-label phase 0 clinical trial involving six patients with metastatic BC showed promising results, with c-MET-CAR-T cell therapy leading to tumor necrosis, hemorrhage, and significant infiltration of T-cells (CD3+, CD4+, and CD8+) and macrophages (CD68+) at the injection sites." (PMID 40281554, 2025). "In summary, these data identify MET activation as not only a prognostic marker for poor clinical outcomes but also as a key contributor to the development of an immunosuppressive microenvironment in PDAC through the functional exhaustion of tumor‐infiltrating CD8+ T cells." (PMID 40673866, 2025). "In a lung cancer model, the anti-tumor effect of fruquintinib was enhanced and could reduce the tumor volume by more than 85% when used in combination with other targeted agents, such as c-MET inhibitors and TKIs, suggesting a combination therapy of its great potential." (PMID 40006092, 2025). "Additionally, combining MET inhibitors with other therapeutic agents has shown remarkable synergistic effects, particularly in overcoming drug resistance and enhancing treatment efficacy across various tumour types." (PMID 40599602, 2025). "The novelty of MYTX‐011, stems from the incorporation of pH‐dependent binding into an anti‐c‐MET antibody, which allows for selective release of its cytotoxic payload, valine citrulline monomethyl auristatin E (vcMMAE), within the acidic microenvironment of tumour cells." (PMID 40619749, 2025). "In this case, the absence of MET mutation in the relapsed tumor sample suggests that this mutation may have been present in sub-clonal populations or was lost during disease progression." (PMID 40386554, 2025). "Additionally, the selective inhibition of VEGFR may trigger compensatory upregulation of the MET pathway, promoting tumor growth." (PMID 40565798, 2025). "Consequently, MET inhibition may sensitize tumor cells to radiation-induced DNA damage, impair repair mechanisms, and enhance apoptosis." (PMID 41573491, 2025). "c-MET and HER2 gene expression were found significantly higher in the study group compared to the controls, with c-MET and HER2 overexpression both associated with pathological stage, muscle invasion, and node involvement, whereas only c-MET overexpression is associated with tumour grade." (PMID 41008920, 2025). "On the one hand, the primary tumor sample displayed the highest number of genes having a great overlap with those already reported to be associated with MPNST, such as the MET Proto-Oncogene, Receptor Tyrosine Kinase (MET), the Hepatocyte Growth Factor (HGF), and others." (PMID 39409151, 2024). "Therefore, MET imbalance is closely related to tumor growth, invasion, and metastasis." (PMID 39451232, 2024). "Moreover, current research indicates their involvement in cancer therapy as drugs targeting oncogenic signaling in tumor cells through c-MET, a receptor tyrosine kinase, not only impedes tumor progression but also blocks neutrophil recruitment into tumors and the draining lymph nodes." (PMID 38474175, 2024).
tumor (continued). "In addition, Prof. Jing-Ji Yang’s team reported a case of MET D1228N mutation in a patient with EPHB4-MET fusion on crizotinib and verified that the mutant tumor may be sensitive to tivantinib, a type III MET inhibitor, in a PDX mouse model." (PMID 38957460, 2024). "A recent study indicated that patients with MET-amplified NSCLCs with concurrent high PD-L1 expression had a decreased tumour response to anti-PD-1 immunotherapy, and neoadjuvant targeted therapy with MET-TKIs might be a better choice for locally advanced MET-amplified NSCLCs." (PMID 38890622, 2024). "However, in most cases, HGF/c-MET signaling inhibits CTL-mediated tumor killing." (PMID 39201787, 2024). "This review sheds light on the complex role of c-MET in cancer pathogenesis, immune evasion, and resistance to therapeutic interventions, highlighting its pivotal role in shaping the tumor microenvironment from an anticancer immune-promoting state to a pro-tumor immune-suppressive state." (PMID 39664377, 2024). "Importantly, the HGF/c-MET signaling pathway is also instrumental in tumor immune escape." (PMID 39201787, 2024). "Furthermore, the interaction between c-MET and other receptors may contribute to the establishment of an immunosuppressive microenvironment, thereby facilitating tumor cells’ evasion of immune surveillance." (PMID 39201787, 2024). "We also detect mutations in MET, which codes for proteins involved in cell growth and survival; PTEN, which is involved in the tumor immune microenvironment; and PIK3CA, which is involved in the tumor immune microenvironment, at 33.33% and 30.30%, respectively." (PMID 39759612, 2024). "Hence, activation of MET signaling may depend on the degree of tumor-stroma interaction, possibly counteracting the beneficial impact of immune checkpoint inhibition (ICi)." (PMID 38386085, 2024). "This suggests that not only NGFR and Ecad but additional correlating genes may underlay cellular plasticity-related regulation of expression, hence therapeutic targeting of the MET receptor signaling pathway by small molecule inhibitors may eliminate several MET+ tumor cell subsets." (PMID 38386085, 2024). "Selpercatinib and pralsetinib are selective RET inhibitors with significant improvement of outcome in patients with tumor harboring RET fusion; however, resistance mechanisms appear frequently, mainly driven by MAPK pathway bypass, secondary RET mutations, or in 5% via MET amplification." (PMID 37876974, 2023). "The MET gene is located on chromosome 7q21‐23 and encodes for a receptor tyrosine kinase, which homodimerizes upon binding to hepatocyte growth factor (HGF) and activates downstream signaling pathways such as RAS/ERK/MAPK and PI3K/AKT, thereby promoting tumorigenesis and tumor progression." (PMID 37326363, 2023). "Consequently, patients with KRAS mutation may exhibit a reliance on MET signaling, specifically downstream of HGF, which is secreted by non-tumor cells and remains undetected under 2-D monolayer culture conditions." (PMID 37381723, 2023). "Regardless of the mechanism involved, the presence of HGF in NSCLC tumours harbouring MET exon 14 skipping strongly indicates the presence of an HGF‐METex14 signalling axis in these patients, which may have a deep impact on a ligand‐dependent oncogene addiction." (PMID 36799689, 2023). "Importantly, based on our data for 7 Ba/Sq samples, we were able to identify higher enhancer activity associated with potential key genes in Basal tumour biology, including cell surface receptors (IL7R, OSMR, EGFR, MET) and transcriptional regulators (BNC2, HMGA2, KLF7, NR3C1)." (PMID 36944729, 2023). "Indeed, it was already clear from studies in cell lines and animal models that substantial reduction of cancer cell viability in vitro and tumor shrinkage in vivo occur only in settings where stable and heritable genetic alterations of MET sustain oncogene ‘addiction’." (PMID 37760640, 2023).
tumor (continued). "For NSCLC, recommendations comprised larotrectinib/entrectinib (unconventional SLC28A3::NTRK2 gene fusion), capmatinib (MET amplification, GCN: 16.7), afatinib (RBPMS::NRG1 gene fusion), and dabrafinib/trametinib in the case of a BRAF p.Val600Glu, and a non-V600E BRAF mutated tumor, respectively." (PMID 38136436, 2023). "Among the nine patients with BPM, driver mutations of primary tumours were determined by NGS, including EGFR mutations (5, 55.6%), which include 19del (4, 44.4%), L858R+A871E + MET (1, 11.1%), ALK (1, 11.1%), ROS1 (1, 11.1%), KRAS (1, 11.1%), and unknown (1, 11.1%)." (PMID 38269023, 2023). "However, inhibiting VEGFA could negate its suppression of HGF-dependent MET phosphorylation and tumor cell migration and lead to a more invasive phenotype." (PMID 37214395, 2023). "MET-amplified (MKN45) and MET-overexpressed (H441) xenograft models of CCA were used to further the preclinical development of an orally bioavailable small-molecule inhibitor LY2801653 targeting MET kinase leading to in vivo anti-tumor effects and in vivo vessel normalization effects." (PMID 38144528, 2023). "Thus, for patients with both sensitizing EGFR mutations and extensive tumor-stroma interactions, additionally targeting HGF/MET may restore the response to EGFR TKIs." (PMID 36647832, 2023). "Using MET-targeted therapy might constitute a promising adjuvant therapy after tumor resection with curative intent, an ideal setting to eradicate the persistence and dissemination of subclinical tumor foci." (PMID 37760640, 2023). "The main driver mutations of primary tumours with LM were determined by NGS, including EGFR L858R (10, 35.7%), EGFR 19del (6, 21.4%), EGFR L858R + MET amplification (1, 3.6%), EGFR L858R+S768I (1, 3.6%), ALK (2, 7.1%), ROS1 (1, 3.6%), negative (5, 17.9%), and unknown (2, 7.1%)." (PMID 38269023, 2023). "Consequently, our analysis of tumor immune infiltrating cells within the TME of THCA tumor revealed that the high expression levels of the DPP4/CTNNB1/MET signature correlate positively with the infiltration levels of tumor-associated macrophages, regulatory T cell, and cancer-associated fibroblast." (PMID 35205190, 2022). "Although the biggest contribution to the therapeutic effect of amivantamab is likely due to EGFR inhibition, it is reasonable to speculate that synergistic targeting of MET must be a factor to help offer better tumor selectivity and avoid major toxicity resulting from WT EGFR inhibition." (PMID 34913823, 2022). "HGF is an activator of the MET pathway, which has been associated with peripheral expansion of neutrophils, as well as with immunosuppressive activity of these cells and lack of tumor T lymphocyte infiltration." (PMID 36010840, 2022). "Therefore, MET has emerged as a key target for tumor therapy." (PMID 35301291, 2022). "CircPTGR1 from exosomes with high metastatic potential and abundance in cells may inhibit the interaction between miR-449a and MET in recipient cells, thus having effects on cells with low metastatic potential, disrupting tumor microenvironment homeostasis, and triggering HCC progression." (PMID 35505392, 2022). "Thus, MET should be secreted by the co‐cultured tumour cells." (PMID 36282889, 2022). "However, recent clinical screens found that amplification and/or activating mutations in the gene encoding KRAS decoupled the RAS-MAPK pathway activity from the MET receptor, constituting the most common form of resistance against MET-targeted therapies in METΔex14-presenting tumours." (PMID 35326531, 2022). "Interestingly, we observed that 92% of RBM10 alterations present in our EGFR-mutant tumor data set did not co-occur with a known EGFR TKI resistance–associated mutation such as EGFR T790M or C797S or MET gene amplification." (PMID 35579943, 2022).
tumor (continued). "Interestingly, a MET amplification was observed in the tumor with two morphologically distinct components: the histological component with a predominantly solid undifferentiated-type growth pattern carried the amplification whilst the other with a predominantly diffuse growth pattern did not." (PMID 36335173, 2022). "However, further in vitro studies are needed to clarify whether the pharmacological co-inhibition of NOTCH and MET pathways have synergistic or additive effects or both on the different malignant features in our tumor context." (PMID 35574376, 2022). "Exosomes from circPTGR1-enriched highly metastatic HCC cells may affect low-metastatic-potential HCC cells by downregulating miR449a-MET interactions in recipient cells, thereby disrupting the homeostasis of the tumor microenvironment and promoting HCC progression." (PMID 35382838, 2022). "In addition, in the previous study of NSCLC, MET amplification was particularly related to the inflammatory microenvironment, indicating that MET-amplified tumor might respond to ICIs." (PMID 35833114, 2022). "EGFR/MET may participate in the metastasis of carcinoma through circulating tumor cells." (PMID 35428350, 2022). "Capmatinib exerts its activity by inhibiting the MET phosphorylation triggered by the binding of HGF or by METamp, as well as MET-mediated phosphorylation of the different downstream signaling proteins, which results in the impaired proliferation and survival of the MET-dependent tumor cells." (PMID 35565287, 2022). "Thus, we investigated the expression of the tumor markers c-MET, RhoA, and CLDN18 by immunohistochemistry (IHC) in a large and extensively characterized Western cohort of resected GC and its correlation with clinicopathological characteristics and survival outcomes." (PMID 35076580, 2021). "The authors concluded that combining the VEGF inhibitor (i.e, sorafenib) and the selective MET inhibitor (i.e, tivantinib) might provide synergistic or additive anti-tumor activity overcoming the resistance to sorafenib in treating advanced solid tumors, including HCC." (PMID 34804015, 2021). "The TRU-type is a lung adenocarcinoma with bronchial epithelial phenotype with initial oncogene mutations such as EGFR, KRAS, and MET amplification, HER2 amplification, and later a second mutation leading to the loss of the BRM protein causing a subsequent poorer differentiation of the tumor." (PMID 34440689, 2021). "In addition, we correlated the MET expression with clinicopathological parameters of HNSCC patients and found an association with human papillomavirus (HPV) as determined by p16 testing, histological grade, tumor location, and nodal (N) status." (PMID 33919702, 2021). "In addition, it was determined that SGX-523, a MET phosphorylation inhibitor, could effectively inhibit the phosphorylation of MET signaling in tumor cells." (PMID 33718248, 2021). "Although MET was highly expressed in the cetuximab-progressed tumors, treatment responsiveness to cetuximab or bevacizumab in each arm was not correlated with the MET expression level, indicating that a MET-dependent tumor cell population may exist." (PMID 34335943, 2021). "Our results demonstrated that the HGF/c-MET pathway could affect tumor proliferation and invasion." (PMID 34261467, 2021). "Interestingly, it is reported that MET inhibition could block the expression of PD-L1 on tumor cells." (PMID 34804015, 2021). "To expand upon their translational potential, we characterized the PDXs response to radiotherapy, demonstrated tumor growth inhibition with MEK inhibition in KRAS mutated PDXs and showed significant growth delay with the MET inhibitor savolitinib in a PDX harboring a MET exon 14 mutation." (PMID 33510214, 2021).
tumor (continued). "Yet, what level (i.e., how many MET gene copies) should be reached in order to induce substantially increased MET-expression and ligand-independent sustained activation of MET signaling with clinically relevant oncogenic effect is unclear and may vary according to tumor type." (PMID 34884673, 2021). "Notably, the expression level of MET was increased during tumor progression." (PMID 34732701, 2021). "The intratumor patterns of MET expression could be an important element to determine a successful response to targeted therapy or to predict possible tumor relapse after treatment and should be better investigated during clinical trials aiming the use of anti-MET drugs in ESCC patients." (PMID 34037097, 2021). "In addition, c-MET in cancer cells is highly sensitive to antibody-induced internalisation, and the high efficiency of cytotoxic payloads to kill tumour cells requires antibody internalisation; therefore, c-MET therapy has inherent potential as a clinical anti-cancer option." (PMID 33816276, 2021). "In addition, MET co-expression with CD133 and/or CD15 was two- to sevenfold that of non-MET expressing bulk tumor cells and MET-overexpression correlated with higher clonogenic and tumorigenic behavior and increased radio-resistance, indicating a possible affiliation of MET with CSC maintenance." (PMID 34055785, 2021). "However, potential side‐effects, such as malignancies due to secondary resistance, might arise in tumours carrying MET amplification and/or MET overexpression." (PMID 32133617, 2020). "Additionally, the activation of short-form Ron, AKT-mammalian target of rapamycin (mTOR), or the Wnt-β-catenin signaling pathway and the over-expression of STAT3, cyclooxygenase-2, c-Myc, (ATP)-binding cassette (ABC) gene 1, or heat shock protein 27 can also induce tumor resistance to MET-TKIs." (PMID 32435640, 2020). "However, TG mice were more resistant to DEN-induced hapatocarcinogenesis at 6, 10, and 12 months of age, showing delayed hepatocyte proliferation and apoptosis, lower tumor incidence, smaller size and fewer number, compared with age-matched WTs, partially through downregulation of MET and EGFR." (PMID 32489479, 2020). "Therefore, whether there are anti-cancer benefits to inhibiting the c-MET dependent recruitment of TANs likely depends on the magnitude of the adaptive anti-tumor response." (PMID 32117721, 2020). "Furthermore, mutations, overexpression, or amplification of the MET gene in some tumor types resulted in aberrant HGF/c-Met axis activity, which induced cell motility and proliferation, promoted tumor development, and led to resistance to radiotherapy and targeted drug therapy in multiple cancers." (PMID 32219093, 2020). "The increased expression of hepatocyte growth factor (HGF) and its physiological receptor tyrosine kinase MET have been shown to be linked to acquired resistance to various tyrosine kinase inhibitors (TKIs), and this phenomenon has been observed in some ALK-positive NSCLC tumour tissues." (PMID 32041944, 2020). "High-level MET gene amplification, protein overexpression, or gene mutations are main mechanisms that induce aberrant activation of the HGF/c-MET pathway, and accumulating evidence has established the role of the c-Met receptor tyrosine kinase in tumor development and metastatic progression." (PMID 31948451, 2020). "In addition to such known findings, a novel MET fusion was identified in a demethylated tumor." (PMID 30760837, 2019). "However, the role of MET in PD-L1 expression in different tumor types is unclear." (PMID 31480591, 2019). "Taken together, these results suggest that MET may be involved in tumor immune evasion." (PMID 31480591, 2019). "This novel MET fusion identified in a C.3 tumor may also increase the cell division rate." (PMID 30760837, 2019).